PINK1 (PTEN induced kinase 1)
Diseases named in the same sentence as PINK1 in open-access papers (continued):
Sharing a sentence is not in itself a finding about the gene and the disease.
infection (27 papers, 2017 to 2025). The state of being infected such as from the introduction of a foreign agent such as serum, vaccine, antigenic substance or organism. "In a murine model of polymicrobial infection, Pink1-deficient macrophage shows a pronounced increase in Δψm, leading to the metabolic rewiring in macrophage activation." (PMID 38266580, 2024). "The model put forward in our previous paper is that anti-mitochondrial CD8 T cells induced by infection in the Pink1−/- mice enter the CNS, causing damage to dopaminergic neurons and leading to motor symptoms." (PMID 33064969, 2020). "PINK1 has also been implicated in liver inflammation due to hepatitis B (HBV) or C virus (HCV) infection." (PMID 31139191, 2019). "Further, PINK1 depletion enhanced the LPS/IFN-γ stimulated proinflammatory phenotype in microglial cells, and adoptive transfer of Pink1-deficient bone marrow promoted Mφ proinflammatory activation, which favored pathogen clearance and increased survival in a murine model of polymicrobial infection." (PMID 33679710, 2020). "The activation of intestinal CD8 + Tc1 cells in PINK1 KO mice at early stages after infection is illustrated by upregulation of Stat3 and Ccr5." (PMID 40404738, 2025). "Specifically, during infection, Pink1−/− monocytes skewed towards “mature” macrophage- and DC-like profiles, with an increased capacity of MHC II presentation." (PMID 40883285, 2025). "We also performed flow cytometric staining of CD4+ and CD8 + T cells in the gut of wild type and PINK1 KO mice following infection." (PMID 40404738, 2025). "We noted a progressive increase in the concentration of inflammatory markers over time which reached significance in wild type and PINK1 KO mice at 2- and 4 weeks post infection (w.p.i.)compared to uninfected mice." (PMID 40404738, 2025). "Our data showed that NCP BVDV infection significantly stimulated the expression of PINK1 and Parkin in a post infection time-dependent manner." (PMID 38443986, 2024). "Infection also provokes mitophagy by increasing the expression of PTEN-induced putative kinase protein 1 (PINK1) and Parkin, as well as Parkin mitochondrial translocation." (PMID 37596671, 2023). "Surprisingly, the mRNA for the kinase-mediated mitophagy (PTEN-induced serine/threonine kinase, PINK1) mRNA was also suppressed during infection." (PMID 37515204, 2023). "Our findings demonstrate that PRV induces mitophagy in JEG-3 cells upon infection, and Drp1-mediated fission and PINK1 were shown to be important modulators of ZIKV viral replication." (PMID 37781396, 2023). "PINK1 downregulation in DENV-infected cells was also evident by a gradual decline in the cleaved PINK1 (PINK1-Cl) during the course of infection." (PMID 36197108, 2022). "Infection of A549 cells with Lnc‐PINK1‐2:5 lentivirus resulted in a dose‐dependent increase in Lnc‐PINK1‐2:5 expression compared with vector control‐transduced cells." (PMID 35201667, 2022). "A follow-up investigation reported that microbial diversity post-infection by C. rodentium was similar in both Pink1-KO mice and their littermate controls, however, the immune activation response was varied." (PMID 35281490, 2022). "In order to determine the effects of Lnc‐PINK1‐2:5 on infection with various strains of influenza virus, we performed an IAV luciferase reporter assay." (PMID 35201667, 2022). "We show that the NS4A protein of JEV localized to the mitochondria and interacted with PINK1 in Huh7 cells during infection with the virus and demonstrate that JEV-NS4A alone is sufficient to induce mitophagy." (PMID 35604158, 2022). "The number of ASVs in both WT and Pink1−/- mice largely remained stable and comparable throughout the infection." (PMID 33064969, 2020). "We also reported that both WT and Pink1−/- mice become colonized to a similar degree, with the infection peaking at day 13 PI with between 108 and 109 fecal colony forming units per gram of feces." (PMID 33064969, 2020).
infection (continued). "Binding analysis revealed that both PINK1 wild type (WT) and PINK1 L347P interacted with TRAF3 in HEK293T cells in a VSV-infection independent manner, whereas the kinase domain-deleted PINK1ΔKD mutant did not." (PMID 31139191, 2019). "The protein expressions of PINK1 and Parkin in A549 cells infected with secondary S. aureus were much higher than those in the control group or the single pathogen group at 12 h and 24 h post-infection, respectively." (PMID 40362402, 2025). "We also noted elevated protein expression of CD11b and CD11c in intestinal Ly6Chigh monocytes from PINK1 KO infected mice, further attesting to the increased differentiation state of PINK1 KO monocytes towards mature, antigen-presenting myeloid cells following infection." (PMID 40404738, 2025). "We first employed an indirect, non-invasive approach using faecal analysis to evaluate whether there was any evidence for enhanced gut inflammation in PINK1 KO mice at different time points after infection." (PMID 40404738, 2025). "However, infection or inflammatory processes can promote depolarization of the mitochondrial membrane, a process known to inhibit the cleavage of PINK1, which leads to the accumulation of PINK1 at the mitochondrial membrane." (PMID 34768767, 2021). "Forty-eight h after infection, the cells were selected with 2.5 μg/ml puromycin (TaKaRa Bio USA, 631305) for 10 d and then collected to examine the efficiency of gene silencing by immunoblot analysis of PINK1." (PMID 31066324, 2019). "Furthermore, infection with VSV in PINK1 knockout macrophages showed similar statistically significant decreases in IFN-β and IL-6 expression." (PMID 31139191, 2019). "We observed by immunohistochemistry that infection with D39 significantly induced the accumulation of PINK1 on the mitochondria in the lung tissue of mice, while both infection with D39ΔspxB and catalase treatment of D39 infection did not increase PINK1-mitochondria interactions." (PMID 30984149, 2019). "Future studies will examine whether a defect in the PINK1-Parkin-Cardiolipin-p62 pathway is responsible for defective mitophagy in WT macrophages following infection with virulent Ehrlichia." (PMID 29049365, 2017). "At 28 days post-infection, qPCR results showed that miR-27a antagomir treatment dramatically suppressed miR-27a expression in lung tissues and spleens of the mice, and increased the expression of Plk2 and Pink1, the two characterized miR-27a’s targets, in the lung tissues 40,41." (PMID 30327467, 2018). "Of note, infection by T. gondii significantly inhibited starvation-induced transcription of autophagy-related genes (i.e., ULK1, BECN1, PINK1, GABARAPL2, SQSTM1, and NBR1), as compared to uninfected serum-starved HFF cultures (i.e., “Control”)." (PMID 37387601, 2023). "We investigated the levels of PINK1 protein and LC3A/B in wild-type BMDMs infected with F. tularensis LVS or F. novicida (MOI 100) 6 h post-infection by western blot analysis." (PMID 37266012, 2023). "Western blot analysis of PINK1 and Parkin in DENV-infected cells also confirmed that PINK1 and Parkin are downregulated in a time-dependent manner during the course of infection." (PMID 36197108, 2022). "At the peak of infection, the level of butyric acid, an SCFA, was disproportionally increased in Pink1-KO mice, possibly implying a compensatory response in early-stage PD pathology." (PMID 35281490, 2022). "The results showed that the expression levels of PINK1 and Parkin were increased in PK-15 and 3D4/2 cells infected by CSFV at different multiplicities of infection." (PMID 28455958, 2017). "In our study, we found that PRRSV infection activates the PINK1/Parkin-mediated mitophagy pathway 24 hours post-infection, but it does not result in the degradation of Tom20." (PMID 39804926, 2025).
infection (continued). "Western blot analysis further revealed that although VacV did not induce apoptosis or affect the levels of several core mitochondrial proteins examined, levels of the mitophagy factor, PINK1 together with phosphorylation at Ser616 in the fission factor, DRP-1 were decreased upon infection." (PMID 38036506, 2023). "Infection with hRSV ON1 resulted in downregulation of the Mfn1, VDAC2, and PINK1 mRNAs." (PMID 37515204, 2023). "Further, the infection does not appear to interact with the Pink1−/- genotype to result in a distinct fecal microbial community." (PMID 33064969, 2020). "Additionally, we interrogated gut function in PINK1 KO mice after infection, as constipation is one of the earliest non-motor symptoms experienced by PD patients." (PMID 40404738, 2025).
neurological diseases (16 papers, 2013 to 2024). "Based on our data showing that GRAF1 plays a unique role in promoting PINK1/Parkin-dependent mitophagy, we surmise that it could regulate the pathological progression of additional cardiometabolic and/or neurological diseases associated with dysfunctions in mitochondrial clearance." (PMID 38081847, 2023). "Parkin RBR E3 ubiquitin-protein ligase (PARKIN)/PTEN-induced kinase 1 (PINK1) pathway has been reported to regulate mitophagy in nervous system diseases." (PMID 37697221, 2024). "Nevertheless, our work have identified that Pink1 may deserve to be evaluated as therapeutic agents in oxidant stress-induced neurological disorders." (PMID 25608948, 2015). "Furthermore, a statistically significant decrease in the levels of the transcript of PINK1 was shown for the neurological disease control group." (PMID 26483988, 2015). "PHBs can prevent apoptosis, inflammation, mitochondrial dysfunction, and autophagy in neurological disorders through different molecules and pathways, such as OPA-1, PINK1/Parkin, IL6/STAT3, Tau, NO, LC3, and TDP43." (PMID 35847581, 2022). "The serine/threonine kinase, PINK1, and the E3 ubiquitin ligase, Parkin, are known to facilitate LC3-dependent autophagosomal encasement and lysosomal clearance of dysfunctional mitochondria, and defects in this process contribute to a variety of cardiometabolic and neurological diseases." (PMID 38081847, 2023).
cardiovascular diseases (13 papers, 2019 to 2025). "Mice that are deficient in Parkin or Pink1 suffer from impaired mitophagy and disorganized small mitochondria, which result in cardiac injuries and exacerbated cardiovascular diseases." (PMID 32351673, 2020). "The current research on mitochondrial autophagy in cardiovascular diseases mainly focuses on the PINK1/parkin pathway." (PMID 40076760, 2025). "Most recently, emerging evidence has shown that PINK1 is related to the Prdx family and protects against cardiovascular disease." (PMID 39763059, 2025). "In the prevention and treatment of cardiovascular diseases, berberine mainly protects cardiac function by activating the PINK1-Parkin, HIF-1α/BNIP3 signaling pathways and promoting mitophagy." (PMID 36034426, 2022). "The discovery of ACR has revealed a new role of circRNAs in adjusting autophagy, and the ACR/PinK1/FAM65B axis may offer a prospective therapeutic target for the treatment of cardiovascular diseases." (PMID 36835653, 2023). "Accumulating evidence suggests that PTEN plays a critical role in cardiovascular disease by inhibiting AKT-dependent pathways (GSK3, FOXO, and mTOR) and PINK1-AMPK signaling cascades." (PMID 33251220, 2020).
metabolic disorders (10 papers, 2014 to 2025). "However, while the death of dopaminergic neurons in the substantia nigra of the brain is the most prominent disease presentation in patients with PINK1 mutations, recent reports have implicated PINK1 gene dysfunction or dysregulation as a potential risk factor for the metabolic disorder T2DM." (PMID 24806840, 2014). "Previous researches showed that in metabolic disorders or oxidative stress, where mitochondrial function and mitophagy are closely intertwined, PINK1 and Parkin act as central mediators, and BNIP3L is upregulated." (PMID 41334630, 2025). "According to the results above, it was reasonable to assume that sodium butyrate could regulate PINK1 and Parkin and trigger mitophagy to obliterate the damaged mitochondria caused by H2O2, which could prevent the intestine from metabolism disorders." (PMID 35132348, 2022).
movement disorder (10 papers, 2016 to 2026). Neurological conditions resulting in abnormal voluntary or involuntary movement, which may impact the speed, fluency, quality and ease of movement. "Mutations in genes that are required for mitophagy, including Vps13D, PINK1, and Parkin, are associated with movement disorders, but gaps exist in our understanding of how Vps13D regulates mitophagy." (PMID 41576035, 2026). "Our findings demonstrated PINK1-deficient rats at 4 months of age had mitochondrial proteomic and functional abnormalities before the onset of Parkinsonian symptoms (6 months) such as the movement disorder, loss of midbrain dopaminergic neurons, or the progressive degeneration present at 9 months." (PMID 26866053, 2016). "MRS1220 and bromocriptine alleviated the movement disorder of PINK1-KD larvae." (PMID 32470327, 2020).
heart disease (7 papers, 2021 to 2024). "These collective findings suggest that dysregulation of GRAF1 phosphorylation may contribute to the exacerbation of cardiac diseases and potentially other conditions associated with defects in PINK1/Parkin-mediated mitochondrial quality control." (PMID 38474413, 2024). "Enhanced mitochondrial autophagy mediated by the PINK1/Parkin signaling pathway can maintain mitochondrial homeostasis in cardiomyocytes and slow the progression of heart disease." (PMID 36238546, 2022). "The regulation of PINK1 expression and enhanced PINK1-dependent mitophagy should form the focus of future treatment strategies for heart disease." (PMID 34751247, 2021). "Defective cardiomyocyte maturation due to lack of PINK1 may ultimately the development of lead to heart diseases." (PMID 37492732, 2023).
kidney disease (6 papers, 2020 to 2025). "Recent studies have demonstrated the close association between PINK1 and many other diseases including cancer, diabetes, and kidney diseases." (PMID 33546409, 2021). "In renal diseases, PINK1/Parkin-mediated mitophagy has been shown to prevent cisplatin-induced apoptosis of renal tubular epithelial cells and tissue damage both in vivo and in vitro." (PMID 40753437, 2025). "Recent studies have revealed a close link between PINK1 and many other diseases including kidney diseases." (PMID 33546409, 2021). "Accumulating evidence suggests that PINK1/Parkin-mediated mitophagy possibly plays a renoprotective role in kidney disease by removing impaired mitochondria and preserving a healthy population of mitochondria." (PMID 32231587, 2020). "Other studies have confirmed the protective role of PINK1/parkin mitophagy in kidney diseases." (PMID 34359852, 2021). "In kidney disease, the PINK1/Parkin pathway was reported to play a dominant role in mitophagy." (PMID 32231587, 2020).
peripheral neuropathy (6 papers, 2012 to 2025). A disorder affecting the peripheral nervous system. "Our results showing the PINK1/Parkin pathway playing a critical role in regulating mitochondrial transport offers one potential explanation of the peripheral neuropathy symptoms observed in these PINK1 or Parkin-linked PD cases." (PMID 22396657, 2012). "Dysfunction of this process could contribute to the loss of DA neurons, the cardinal feature of PD, as well as the peripheral neuropathy symptom associated with particular PINK1 or Parkin mutations." (PMID 22396657, 2012). "The function of PINK1 in mitochondrial transport may contribute to PD pathogenesis in DA neurons and underlie the peripheral neuropathy symptoms associated with certain PINK1 mutations in some PD patients." (PMID 22396657, 2012). "In some PINK1- or Parkin-linked PD patients, symptoms of peripheral neuropathy were also reported." (PMID 22396657, 2012). "Although the symptoms of PD patients mainly arise from the loss of DA neurons, some PD patients carrying particular PINK1 and Parkin mutations developed peripheral neuropathy with unknown cause." (PMID 22396657, 2012). "In summary, our data show that niclosamide ameliorates the thermal hyperalgesia phenotype and mitochondrial dysfunction in paclitaxel-induced peripheral neuropathy in a PINK1-dependent manner." (PMID 35453613, 2022). "In this study, we report that the PINK1 activator niclosamide exhibits therapeutic potential in paclitaxel-induced peripheral neuropathy." (PMID 35453613, 2022). "In this study, we show that the small-molecule PINK1 activator niclosamide exhibits therapeutic potential for paclitaxel-induced peripheral neuropathy." (PMID 35453613, 2022). "In conclusion, our study provides evidence that the ectopic expression of PINK1 ameliorates the thermal hypersensitive phenotype of paclitaxel-induced peripheral neuropathy." (PMID 32941465, 2020). "In this study, we report for the first time the neuroprotective function of PINK1 in a paclitaxel-induced peripheral neuropathy model." (PMID 32941465, 2020). "Here, we examined the effect of PINK1 expression on CIPN using a recently established paclitaxel-induced peripheral neuropathy model in Drosophila larvae." (PMID 32941465, 2020). "By monitoring mitochondrial movement in live Drosophila larval motor neurons, which possesses long axons and could serve as a model system for studying peripheral neuropathy, we provide evidence that PINK1 directly regulates mitochondrial transport." (PMID 22396657, 2012). "Although the precise mechanism by which PINK1 expression suppresses paclitaxel-induced mitochondrial dysfunction in sensory neurons remains to be explored, our results highlight PINK1 as a potential target for the treatment of paclitaxel-induced peripheral neuropathy." (PMID 32941465, 2020). "To understand how PINK1 mitigates paclitaxel-induced thermal hypersensitivity, we next examined whether paclitaxel induces mitochondrial dysfunction in our paclitaxel-induced peripheral neuropathy model." (PMID 32941465, 2020). "Our results confirm that PINK1 is a potential target for CIPN treatment and suggest that niclosamide is a candidate for the treatment of paclitaxel-induced peripheral neuropathy." (PMID 35453613, 2022).
adenocarcinoma (5 papers, 2020 to 2025). A common cancer characterized by the presence of malignant glandular cells. "Similarly, several analyses in NSCLC patients revealed that high expression levels of PINK1 were associated with a compromised treatment response and were identified as an independent prognostic factor for adenocarcinoma." (PMID 37940999, 2023).
mitochondrial disease (4 papers, 2015 to 2023). "However, the reverse was seen in the PD and mitochondrial disease cases (effect size<0.25), showing a significant loss of response compared to the controls (ANOVA, p = 0.035, PD, p = 0.041, MITO, SIRT3; PD, p = 0.006, MITO, p = 0.008, PINK1)." (PMID 37553379, 2023).
bacterial infection (3 papers, 2021 to 2025). "Future endeavors aimed at unraveling the molecular interactions involving ATG5, PINK1, Parkin, and PHB2, combined with more comprehensive functional assays, hold the potential to provide insights into the intricate role of ATG5 in mitophagy, particularly in the context of bacterial infections." (PMID 40529614, 2025).